TRAIP (TRAF interacting protein)
Description:
E3 ubiquitin ligase required to protect genome stability in response to replication stress. Acts as a key regulator of interstrand cross-link repair, which takes place when both strands of duplex DNA are covalently tethered together, thereby blocking replication and transcription (By similarity). Controls the choice between the two pathways of replication-coupled interstrand-cross-link repair by mediating ubiquitination of MCM7 subunit of the CMG helicase complex (By similarity). Short ubiquitin chains on MCM7 promote recruitment of DNA glycosylase NEIL3 (By similarity). If the interstrand cross-link cannot be cleaved by NEIL3, the ubiquitin chains continue to grow on MCM7, promoting the unloading of the CMG helicase complex by the VCP/p97 ATPase, enabling the Fanconi anemia DNA repair pathway (By similarity). Only catalyzes ubiquitination of MCM7 when forks converge (By similarity). Also involved in the repair of covalent DNA-protein cross-links (DPCs) during DNA synthesis: promotes ubiquitination of DPCs, leading to their degradation by the proteasome (By similarity). Has also been proposed to play a role in promoting translesion synthesis by mediating the assembly of 'Lys-63'-linked poly-ubiquitin chains on the Y-family polymerase POLN in order to facilitate bypass of DNA lesions and preserve genomic integrity. The function in translesion synthesis is however controversial. Acts as a regulator of the spindle assembly checkpoint. Also acts as a negative regulator of innate immune signaling by inhibiting activation of NF-kappa-B mediated by TNF. Negatively regulates TLR3/4- and RIG-I-mediated IRF3 activation and subsequent IFNB1 production and cellular antiviral response by promoting 'Lys-48'-linked polyubiquitination of TNK1 leading to its proteasomal degradation.
Synonyms: RNF206; TRIP; SCKL9
Tractability: Antibody: the Human Protein Atlas places it where antibodies can reach. PROTAC: UniProt records ubiquitination sites on it; ubiquitination databases record sites on it.
Gene: Protein-coding gene on chromosome 3 (49,828,595 to 49,856,597, reverse strand). Ensembl gene ENSG00000183763.
Subcellular location: Nucleus, nucleoplasm; Nucleus, nucleolus; Chromosome; Cytoplasm; Cytoplasm, perinuclear region
Subcellular location (Human Protein Atlas): Cytosol; Plasma membrane
Pathways (Reactome):
Immune System: Antigen processing: Ubiquitination & Proteasome degradation
Gene Ontology:
Molecular function: identical protein binding; protein binding; ubiquitin protein ligase activity; ubiquitin-protein transferase activity
Biological process: DNA damage response; negative regulation of tumor necrosis factor-mediated signaling pathway; protein ubiquitination; replication fork processing; apoptotic process; protein-DNA covalent cross-linking repair; signal transduction; negative regulation of interferon-beta production; negative regulation of signal transduction
Cellular component: chromosome; nucleolus; nucleoplasm; plasma membrane; site of DNA damage; nucleus; cytoplasm; perinuclear region of cytoplasm
Genetic constraint (gnomAD): Loss-of-function variants: 37 observed, 65.83 expected, observed/expected ratio (o/e) 0.56, 90% interval 0.43 to 0.74. The upper end of that interval is the gene's LOEUF score, 0.74, which puts it in group 3 of 6, group 1 being the genes least tolerant of losing a copy. Missense variants: 470 observed, 594.91 expected, observed/expected ratio (o/e) 0.79, 90% interval 0.73 to 0.85. Synonymous variants: 186 observed, 228.41 expected, observed/expected ratio (o/e) 0.81, 90% interval 0.72 to 0.92.
Homologues: Orthologues: chimpanzee TRAIP (99% identical), macaque TRAIP (96% identical), pig TRAIP (85% identical), rabbit TRAIP (85% identical), dog TRAIP (84% identical), guinea pig TRAIP (82% identical), rat Traip (81% identical), mouse Traip (79% identical), tropical clawed frog traip (52% identical), zebrafish traip (47% identical).
Diseases named in the same sentence as TRAIP in open-access papers:
TRAIP is named in the same sentence as 31 diseases in open-access papers, as found by Europe PMC text mining. Sharing a sentence is not in itself a finding about the gene and the disease. The quoted sentences say what the papers report.
primordial dwarfism (6 papers, 2016 to 2023). "Mutations in TRAIP were also found in patients with primordial dwarfism and the patient mutation (R18C) was defective for MCM7 polyubiquitylation and repairing ICL lesions in Xenopus egg extracts." (PMID 36594163, 2023). "TRAIP is essential for cell viability, and mutations in TRAIP ubiquitin ligase activity lead to primordial dwarfism in patients." (PMID 37604812, 2023). "The TRAIP E3 ubiquitin ligase is essential for genome integrity, mutations lead to primordial dwarfism in patients." (PMID 37604812, 2023). "TRAIP is essential for mouse development, whereas RING mutations or truncating mutations in human TRAIP are viable but lead to a form of primordial dwarfism that is associated with a defective DNA damage response." (PMID 33590678, 2021). "Recent whole-exome sequencing (WES) studies demonstrated that TRAIP is associated with primordial dwarfism." (PMID 27405720, 2016). "TRAIP is involved in the DNA damage response (DDR) and multiple DNA repair pathways and physiological importance of TRAIP functions has been manifested by the identification of biallelic mutations of TRAIP gene in individuals presented with primordial dwarfism." (PMID 36594163, 2023). "TRAIP mutations in humans induce microcephalic primordial dwarfism." (PMID 30595436, 2019). "Because TRAIP is mutated in primordial dwarfism patients, these findings might improve our understanding of this catastrophic human disease." (PMID 27405720, 2016). "Both DPC ubiquitylation and proteolysis were largely restored by recombinant wild-type (WT) TRAIP (lanes 13–18), but not a TRAIP mutant harboring an amino acid substitution in the RING domain (R18C) (lanes 19–24) that causes primordial dwarfism." (PMID 30595436, 2019).
Seckel syndrome (6 papers, 2018 to 2023). A rare autosomal recessive inherited syndrome caused by mutations in the ATR gene, RBBP8 gene, CENPJ gene, CEP152 gene, CEP63 gene, NIN gene, DNA2 gene, or TRAIP gene. "Other forms of Seckel syndrome are caused by mutations in genes associated with cell growth (TRAIP), genomic integrity and repair (ATR, NSMCE2, DNA2, and RBBP8), centrosome function (NIN, CEP63)." (PMID 29504900, 2018). "Seckel syndrome is genetically heterogeneous, and mutations in DDR genes (ATRIP and ATR), DNA repair factors (NSMCE2, DNA2, TRAIP and CtIP) and components of the centrosome (NIN, CEP63, CEP152 and CENPJ) have been reported." (PMID 32994318, 2020). "Notably, however, TRAIP-deficient patients were not reported to characterise with cancer predisposition, similarly to other Seckel syndrome patients." (PMID 37604812, 2023).
osteosarcoma (5 papers, 2021 to 2024). A usually aggressive malignant bone-forming mesenchymal neoplasm, predominantly affecting adolescents and young adults. "We found that TRAIP levels were associated with metastasis-free survival and overall survival in patients with osteosarcoma." (PMID 34349117, 2021). "To explore the mechanisms underlying TRAIP’s ability to promote osteosarcoma progression, we employed mass spectrometry to identify the potential binding partners of TRAIP in 293 T cells." (PMID 34349117, 2021). "TRAIP enhances osteosarcoma invasion and proliferation through the modulation of IGFBP3/AKT by promoting the degradation of KANK1, which is a tumor suppressor." (PMID 36999051, 2023). "To determine the role of TRAIP in osteosarcoma, we silenced its expression in osteosarcoma cell lines using two different short-hairpin RNAs (shRNAs)." (PMID 34349117, 2021). "To get further insight into the mechanisms underlying the tumor-promoting roles of TRAIP in osteosarcoma, we performed mass spectrometry and identified KANK1 as a TRAIP substrate." (PMID 34349117, 2021). "In this study, we performed bioinformatics analyses to investigate the role of TRAIP in osteosarcoma." (PMID 34349117, 2021). "To evaluate the relevance of KANK1 in TRAIP’s ability to promote osteosarcoma progression, we generated osteosarcoma cells with stable knockdown of TRAIP, KANK1, and the combination of the two." (PMID 34349117, 2021). "In conclusion, we used bioinformatics to identify DEGs between CTCs and metastatic lesions in osteosarcoma and identified TRAIP as a key DEG with prognostic significance." (PMID 34349117, 2021). "We identified TRAIP as a key differentially expressed gene with prognostic significance in osteosarcoma." (PMID 34349117, 2021). "Among these genes, TRAIP displayed a significant prognostic value in osteosarcoma." (PMID 34349117, 2021). "We also stably overexpressed TRAIP in osteosarcoma cell lines using lentiviruses." (PMID 34349117, 2021). "TRAIP silencing decreased the viability of osteosarcoma cells." (PMID 34349117, 2021). "We demonstrated that TRAIP regulated the proliferation and invasion of osteosarcoma cells." (PMID 34349117, 2021). "We also found that TRAIP regulated the proliferation and invasion of osteosarcoma cells." (PMID 34349117, 2021). "We confirmed that TRAIP promoted osteosarcoma progression by regulating protein ubiquitination." (PMID 34349117, 2021). "Aberrant TRAIP overexpression promoted osteosarcoma cell proliferation and invasion." (PMID 34349117, 2021). "TRAIP overexpression enhanced osteosarcoma cell proliferation and invasion." (PMID 34349117, 2021). "We also found that TRAIP enhanced the malignancy of osteosarcoma cells." (PMID 34349117, 2021). "We also found that TRAIP regulated IGFBP3 expression through KANK1 in osteosarcoma cells." (PMID 34349117, 2021). "Overexpression of TRAIP could promote the migratory/invasive ability of osteosarcoma cells." (PMID 36064576, 2023). "Nevertheless, the role of TRAIP in osteosarcoma remains unknown." (PMID 34349117, 2021). "Furthermore, transwell assay revealed that TRAIP silencing suppressed osteosarcoma cell invasion." (PMID 34349117, 2021). "We also investigated the protein of levels of TRAIP and KANK1 in a tissue microarray of osteosarcoma specimens (n = 70)." (PMID 34349117, 2021). "We found that there was a relatively weak correlation between TRAIP and KANK1 in osteosarcoma tissues (Spearman r = −0.2516, P = 0.0485)." (PMID 34349117, 2021). "Experimental results showed that TRAIP downregulates the expression of IGFBP3 by promoting the ubiquitination and degradation of KANK1, thereby activating the AKT pathway and promoting the proliferation and invasion of osteosarcoma cells." (PMID 39062505, 2024). "In addition, TRAIP-mediated downregulation of KANK1 can enhance the invasion and proliferation of osteosarcoma cells through the IGFBP3/AKT pathway." (PMID 35320976, 2022).
osteosarcoma (continued). "TRAIP knockdown resulted in increased KANK1protein levels but did not affect KANK1 mRNA levels in any of the three osteosarcoma cell lines." (PMID 34349117, 2021). "In addition, we found that TRAIP promoted KANK1 polyubiquitination and subsequent degradation, downregulating IGFBP3 and activating the AKT pathway in osteosarcoma cells." (PMID 34349117, 2021). "Notably, TRAIP activated the AKT pathway by promoting KANK1 polyubiquitination and degradation and downregulating IGFBP3 in osteosarcoma cells." (PMID 34349117, 2021).
breast carcinoma (4 papers, 2015 to 2023). "Both measures with high ranks indicated 5 SNPs (SALL1 rs10521222; HLA-DQA1 rs9271608; DUSP1 rs17658229; APOC1 rs4420638; and TRAIP rs2352975) and 3 lifestyles (duration of OC and E + P use and BMI) as the most influential variables for breast cancer." (PMID 33441805, 2021). "The UALCAN database was used to analyze the expression of TRAIP in breast cancer." (PMID 36064576, 2023). "Since overexpression of TRAIP has been reported in basal cell carcinomas, breast cancer and melanomas (unpublished results), targeting TRAIP or its substrates may provide new possibilities for therapeutic interventions in tumors." (PMID 26369285, 2015). "Consequently, these findings suggested that silencing of TRAIP may inhibit cell migration and invasion by suppressing EMT in breast cancer cells." (PMID 36064576, 2023).
dwarfism (4 papers, 2023 to 2025). "As mutations of TRAIP lead to microcephalic dwarfism, deeper understanding of TRAIP activity and regulation will shed light on sources of development of this disorder." (PMID 40637231, 2025). "TRAIP-deficient human cells have been shown to proliferate slowly even in the absence of exogenous DNA damage and the reduction of cellular proliferation during development is a likely cause of microcephalic dwarfism observed in patients with TRAIP mutations." (PMID 37604812, 2023). "Mutations in TRAIP were found in patients suffering from primodial dwarfism and the recombinant protein carrying the patient mutation (R18C) still forms short ubiquitin chains on MCM7 but fails to repair cisplatin-ICL repair while promoting TMP-ICL repair in Xenopus system." (PMID 36594163, 2023).
liver cancer (4 papers, 2020 to 2023). An epithelial or non-epithelial malignant neoplasm that arises from the liver. "TRAIP was found to be overexpressed in liver cancer, and its expression levels were associated with poor prognosis in patients with liver cancer." (PMID 34349117, 2021). "TRAIP has carcinogenic properties, and it is negatively correlated with the prognosis of patients with liver cancer and lung cancer, suggesting that TRAIP may be a promising therapeutic target for those types of cancer." (PMID 36064576, 2023). "Moreover, inhibition of TRAIP induced apoptosis in liver cancer cells." (PMID 34349117, 2021).
lung carcinoma (4 papers, 2016 to 2023). "As for SLC7A11-AS1, it can confer malignant progression by repressing miR-4775 and TRAIP expression in lung cancer and reduce tumor growth via the ASK1-p38 MAPK/JNK pathway in gastric cancer." (PMID 37312123, 2023). "The elevated expression of TRAIP in cancer samples promoted tumor metastasis and poor survival in patients with lung cancer." (PMID 35884544, 2022). "H-scoring in every sample indicated that nuclear expression of TRAIP greatly decreased in human lung cancer patient tissues (median H-score, 46.9) compared with that in each matched normal adjacent tissues (median H-score, 156.6)." (PMID 26781088, 2016). "Together, these results suggest that low level of nuclear TRAIP in human lung cancer might be involved in incidence of genome instability—the hallmarks of cancer." (PMID 26781088, 2016).
lung adenocarcinoma (3 papers, 2016 to 2020). A carcinoma that arises from the lung and is characterized by the presence of malignant glandular epithelial cells. "Reduced expression level of TRAIP is associated with a human lung adenocarcinoma." (PMID 26781088, 2016). "The results explained that the high expression of UBE2C, UCHL1, TRAIP, TNNT1, TNNI3, and RAC3 were associated with poor overall survival of lung adenocarcinoma patients (p < 0.05)." (PMID 33050659, 2020). "To support this idea, we verified TRAIP expression in human lung adenocarcinoma patient tissues and matched normal adjacent tissues (≥2 cm away from cancer) using a tissue microarray." (PMID 26781088, 2016).
basal cell carcinoma (2 papers, 2015 to 2019). A carcinoma involving the basal cells. "Recent work showed that TRAIP expression is increased in breast epithelial cell lines, in breast tumors, and in basal cell carcinomas (BCC) with a concomitant decrease in CYLD expression, a tumor suppressor interacting with TRAIP." (PMID 26369285, 2015).
breast tumors (2 papers, 2015 to 2023). "The results showed that TRAIP was expressed higher in primary breast tumors (n = 1097) than in normal tissues (n = 114, P < 0.001)." (PMID 36064576, 2023). "In addition, TRAIP interacts with CYLD and Syk, two tumor suppressors implicated in the formation of skin appendages tumors such as cylindroma, trichoepithelioma and spiradenoma (CYLD) and of melanomas and breast tumors (CYLD and Syk)." (PMID 26369285, 2015).
colon carcinoma (2 papers, 2023 to 2025). "To answer this, we have generated auxin-inducible degrons of TRAIP in the colon carcinoma HCT116 cell lines and immortalised retinal pigment epithelial cells hTERT-RPE1, which facilitate the degradation of TRAIP within 30 min of auxin (IAA) addition to the cell media." (PMID 37604812, 2023).
cardiomyopathy (1 paper, 2020). A disease of the heart muscle or myocardium proper. "We assumed that miR-1246 might target UBE2C, TNNT1, TRAIP, and UCHL1 during the regulation of ubiquitin-mediated proteolysis, glycosaminoglycan binding, DNA metabolism, the PI3K–Akt–mTOR signaling pathway, the neurotrophin and cardiomyopathy signaling pathway, and the MAPK signaling pathway." (PMID 33050659, 2020).
cervical cancer (1 paper, 2023). A primary or metastatic malignant neoplasm involving the cervix. "The intersection of LASSO and SVM-RFE analyses revealed eight hub genes in cervical cancer, which were RBBP4, SRM, GCH1, USP14, TRAIP, CBX4, VEZF1, and TOM1." (PMID 36999051, 2023).
dyslexia (1 paper, 2025). A learning disorder characterized by an impairment in processing written words. "Four genes – SORCS3, TCTA, TRAIP and AMT – shown to be pleiotropic had previously been associated with dyslexia and ADHD in individual GWAS studies and are very strong pleiotropic candidate genes." (PMID 39009701, 2025).
glioblastoma (1 paper, 2023). The most malignant astrocytic tumor (WHO grade IV). "We replicated most of these associations in glioblastoma (Klughammer cohort) where 14 of 17 genes were also positively associated with TERT expression, including four genes related to DNA repair (XRCC2, MSH5, TRAIP, BRIP1)." (PMID 37418389, 2023).
lymph node metastasis (1 paper, 2023). "In the present study, the expression of TRAIP in TNBC was found to be higher than that in adjacent normal tissues for the first time, and the expression in lymph node metastasis was significantly higher than that in primary lymph node metastasis." (PMID 36064576, 2023).
lymphoma (1 paper, 2024). A malignant (clonal) proliferation of B- lymphocytes or T- lymphocytes which involves the lymph nodes, bone marrow and/or extranodal sites. "Moreover, in chicken DT40 B lymphoma cells, TRAIP withstands DNA topoisomerase II-induced chromosome breakage, suggesting that TRAIP may be a therapeutic target for DNA damage-induced cancer." (PMID 38630271, 2024).
myelodysplastic syndrome (1 paper, 2022). A clonal hematopoietic disorder characterized by dysplasia and ineffective hematopoiesis in one or more of the hematopoietic cell lines. "Tifab (TRAF-interacting protein with forkhead-associated domain B) has been manifested to regulate hematopoiesis through Toll-like receptor (TLR)-TRAF6 complex and loss of Tifab induces BM failure and myelodysplastic syndrome (MDS)." (PMID 35740994, 2022).
triple-negative breast carcinoma (1 paper, 2023). An invasive breast carcinoma which is negative for expression of estrogen receptor (ER), progesterone receptor (PR), and human epidermal growth factor receptor 2 (HER2). "At present, few studies on the relationship between TRAIP and triple negative breast cancer (TNBC) were reported." (PMID 36064576, 2023).